SNORA71 (Small nucleolar RNA SNORA71 )
Synonyms: LOC124904975
Gene: Small nucleolar RNA gene on chromosome 20 (38,442,036 to 38,442,169, forward strand). Ensembl gene ENSG00000201811.
Gene Ontology:
Biological process: RNA processing
Cellular component: nucleolus
Homologues: Orthologues: chimpanzee SNORA71 (99% identical), guinea pig SNORA71 (71% identical), guinea pig SNORA71 (70% identical), rat Snora71c (70% identical), dog SNORA71 (69% identical), mouse Gm23925 (69% identical), rabbit SNORA71 (68% identical), pig SNORA71 (67% identical), rabbit SNORA71 (67% identical), rabbit SNORA71 (66% identical), rat LOC120100208 (65% identical). Paralogues in human: SNORA71C (72% identical), SNORA60 (69% identical), SNORA71A (68% identical), SNORA71D (68% identical), SNORA71E (67% identical), SNORA71 (59% identical), SNORA71 (58% identical).
Diseases named in the same sentence as SNORA71 in open-access papers:
SNORA71 is named in the same sentence as 8 diseases in open-access papers, as found by Europe PMC text mining. Sharing a sentence is not in itself a finding about the gene and the disease. The quoted sentences say what the papers report.
breast carcinoma (1 paper, 2025). "snorA38 and snoRA71 were identified as part of a 20 snoRNA/scaRNA signature associated with breast cancer brain metastases." (PMID 41510246, 2025).
colorectal cancer (1 paper, 2025). A primary or metastatic malignant neoplasm that affects the colon or rectum. "snoRA71 is highly expressed and has been identified as a prognostic marker of lung cancer, hepatocellular carcinoma (HCC), multiple myeloma, and colorectal cancer." (PMID 41510246, 2025).
glioblastoma (1 paper, 2025). The most malignant astrocytic tumor (WHO grade IV). "A Pan-cancer study using TCGA small RNA-seq data from 31 cancer types (excluding glioblastoma) identified 46 clinically relevant snoRNAs, including snoRA71, which showed alterations in at least 12 different tumor types." (PMID 41510246, 2025).
cancer (1 paper, 2025). A tumor composed of atypical neoplastic, often pleomorphic cells that invade other tissues. "SnoRNAs with elevated expression in GSC and GBM lines (snoRA38, snoRA51, snoRA71, and snoRA75) have been previously implicated in cancer development." (PMID 41510246, 2025).
tumor (1 paper, 2025). "SnoRA71 knockdown affected proliferation, migration, invasion, and tumor growth." (PMID 41510246, 2025).
SNORA71 also shares sentences with these, for which no sentence is quoted: hepatocellular carcinoma (1 paper); lung carcinoma (1); multiple myeloma (1).